LCE7A (late cornified envelope 7A)
Description:
Precursors of the cornified envelope of the stratum corneum.
Tractability: No criterion of Open Targets' tractability assessment is met for any kind of drug.
Gene: Protein-coding gene on chromosome 1 (152,859,996 to 152,861,252, forward strand). Ensembl gene ENSG00000285946.
Gene Ontology:
Biological process: epidermis development
Homologues: Orthologues: dog LCE7A (65% identical), pig LCE7A (61% identical), rat Lce7a (60% identical), mouse 2210017I01Rik (57% identical).